CD68 (CD68 molecule)
Diseases named in the same sentence as CD68 in open-access papers (continued):
Sharing a sentence is not in itself a finding about the gene and the disease.
tumor (continued). "There were no significant changes for tumor-infiltrating CD20 (B cell), CD45RO (activated/memory T cell), or CD68 (tissue macrophage) positive cell populations (data on file, Incyte)." (PMID 35288468, 2022). "Here we found that LMR calculated in peripheral blood specifically and significantly correlated with stromal infiltration of CD68+ and CD163+ macrophages but not tumor tissue infiltration." (PMID 35958590, 2022). "In addition, by using dual IF staining, we confirmed that Gal-9 was mainly expressed in CD68+CD163+ KCs rather than tumor cells or M2 macrophages, indicating that Gal-9 may be involved in the formation of immune suppressive microenvironment in HBV-associated HCC." (PMID 35202002, 2022). "In MLL-tumors, all tumor cells were CK7- and CD68-, while almost all tumor cells were BrdU + (data not shown)." (PMID 35551231, 2022). "The volume density of remaining BrdU + cells (CD68-/CK7-/BrdU +) was low and did not significantly differ between animals with MLL-tumors and tumor-free controls." (PMID 35551231, 2022). "Pretreatment ALC did not correlate with the number of tumor-infiltrating CD4-, CD8-, or CD68-positive cells." (PMID 35385334, 2022). "Immunohistochemical staining showed that the tumor cells were negative for cytokeratin AE1/AE3, whereas the non-neoplastic osteoclast-like giant cells were positive for CD68." (PMID 35484362, 2022). "As for cluster 13, CD68 was strongly expressed in stage I and CD204 in the advanced tumor, but MAFB was not expressed." (PMID 36077342, 2022). "Similar interactions were noted between T cells and CD68+PD-L1+ macrophages, which were particularly prevalent in HRD-Del cases, but largely absent in FBI tumours." (PMID 36517593, 2022). "Immunohistochemical staining showed that the tumor cells were negative for AE1/AE3, whereas the non-neoplastic osteoclast-like giant cells were positive for CD68." (PMID 35484362, 2022). "In the tumor capsule, no dendritic cells, 65% of CD45 positive cells, 10% of CD11b positive cells, and 5% of CD68 positive cells were detected." (PMID 33921688, 2021). "In the control group, iNOS density in the tumor area was significantly lower compared to the BGS treatment group (control 33.6 ± 9.4; BGS 67.1 ± 8.8), and many of the CD68 cells were iNOS negative (white arrows)." (PMID 34282238, 2021). "In the tumor capsule, no dendritic cells, 70% of CD45 positive cells, 10% of CD11b positive cells, and no CD68 positive cells were detected." (PMID 33921688, 2021). "In the tumor capsule, 25% of dendritic cells, 10% of CD45 positive cells, no CD11b positive cells, and no CD68 positive cells were detected." (PMID 33921688, 2021). "In the tumor capsule, no dendritic cells, 35% of CD45 positive cells, no CD11b positive cells, and 5% of CD68 positive cells were detected." (PMID 33921688, 2021). "We found that CD68 (macrophage), but not CD177 (neutrophil), is positively correlated with CD40 in both normal (r = 0.42) and tumor (r = 0.38) tissues." (PMID 34758832, 2021). "Immunohistochemistry, the tumor cells were diffusely positive for S-100 protein, SOX-10 and CD68, while they were completely negative for desmin, DOG-1, AE1/AE3 and P63." (PMID 34243786, 2021). "In the tumor capsule, no dendritic cells, 20% of CD45 positive cells, no CD11b positive cells, and no CD68 positive cells were detected." (PMID 33921688, 2021). "In the tumor capsule, no dendritic cells, 30% of CD45 positive cells, 25% of CD11b positive cells, and no CD68 positive cells were detected." (PMID 33921688, 2021). "Coexpression of KLK6 with KRT19, αSMA or CD68 was independent of tumour stage, while KLK6 was coexpressed with KRT19 and CD68 in the invasive tumour area." (PMID 34439122, 2021).
tumor (continued). "In the tumor capsule, 35% of dendritic cells, 5% of CD45 positive cells, 30% of CD11b positive cells, and no CD68 positive cells were detected." (PMID 33921688, 2021). "In the tumor capsule, no dendritic cells, 40% of CD45 positive cells, 5% of CD11b positive cells, and 5% of CD68 positive cells were detected." (PMID 33921688, 2021). "In the tumor capsule, no dendritic cells, 20% of CD45 positive cells, 55% of CD11b positive cells, and no CD68 positive cells were detected." (PMID 33921688, 2021). "In the tumor capsule, 15% of dendritic cells, 20% of CD45 positive cells, 45% of CD11b positive cells, and no CD68 positive cells were detected." (PMID 33921688, 2021). "The TAM antigens CD68 and CD163 were mainly expressed at the tumour invasive front and stroma, while no expression or only weak expression was observed in tumour nests." (PMID 34884696, 2021). "In the tumor capsule, 25% of dendritic cells, no CD45 positive cells, no CD11b positive cells, and no CD68 positive cells were detected." (PMID 33921688, 2021). "In the tumor capsule, 70% of dendritic cells, 30% of CD45 positive cells, 20% of CD11b positive cells, and no CD68 positive cells were detected." (PMID 33921688, 2021). "In contrast, the tumor cells were nonreactive for SF-1, inhibin alpha, desmin, HHF35, HMB45, Melan A, MITF, c-kit, DOG1, cytokeratin AE1/AE3, h-caldesmon, STAT6, CD68, MDM2, CDK4, c17, DHEAST, 3BHSD, CD31, Factor 8, and ERG." (PMID 34797454, 2021). "Immunohistochemically, the tumor cells were negative for CD20, CD79a, CD3, CD5, c-kit, CD34, and TdT and positive for myeloperoxidase, CD33, CD68, and CD163." (PMID 34970464, 2021). "In the tumor capsule, no dendritic cells, 5% of CD45 positive cells, 25% of CD11b positive cells, and no CD68 positive cells were detected." (PMID 33921688, 2021). "Another difference we detected was that tumor PD-L1 expression correlated with TILs (CD4, CD8) and macrophages (CD68) in extracerebral sites but not in the brain." (PMID 32974852, 2021). "While KLK6-expressing stromal cells were not correlated with (non)invasive tumour areas and tumour stage, KLK6-expressing CD68+ cells were present in invasive tumour areas but not in noninvasive tumour areas and did not correlate with tumour stage." (PMID 34439122, 2021). "In the tumor capsule, 20% of dendritic cells, 15% of CD45 positive cells, 30% of CD11b positive cells, and no CD68 positive cells were detected." (PMID 33921688, 2021). "In the tumor capsule, no dendritic cells, 65% of CD45 positive cells, no CD11b positive cells, and 5% of CD68 positive cells were detected." (PMID 33921688, 2021). "In the tumor capsule, no dendritic cells, 80% of CD45 positive cells, 5% of CD11b positive cells, and no CD68 positive cells were detected." (PMID 33921688, 2021). "In the tumor capsule, no dendritic cells, 25% of CD45 positive cells, 50% of CD11b positive cells, and no CD68 positive cells were detected." (PMID 33921688, 2021). "Collectively, our findings indicated that the primary S100A9-expressing cells in adjacent nontumoral tissue are CD15+ neutrophils, and both CD68+ Mφs and CD15+ neutrophils highly express S100A9 in HCC tumor tissues." (PMID 34157683, 2021). "Tumor cells were nonreactive for SF-1, inhibin alpha, desmin, HHF35, HMB45, Melan A, MITF, c-kit, DOG1, cytokeratin AE1/AE3, h-caldesmon, STAT6, CD68, MDM2, CDK4, c17, DHEAST, 3BHSD, CD31, Factor 8, and ERG." (PMID 34797454, 2021). "Immunohistochemistry demonstrated that PD-L1 was preferentially expressed on CD68+ macrophages in the tumor microenvironment of HCC, suggestive of its expression in TAMs rather than in T cells or tumor cells (P < 0.05)." (PMID 33946835, 2021). "In the tumor capsule, no dendritic cells, 45% of CD45 positive cells, 5% of CD11b positive cells, and no CD68 positive cells were detected." (PMID 33921688, 2021). "In the tumor capsule, no dendritic cells, 15% of CD45 positive cells, no CD11b positive cells, and no CD68 positive cells were detected." (PMID 33921688, 2021).
tumor (continued). "The tumor cells were diffusely positive for S-100 protein, SOX-10 and CD68, while they were completely negative for desmin, DOG-1, AE1/AE3 and P63." (PMID 34243786, 2021). "In the MZL tumor samples in contrast, HRG expression did not correlate with an increased presence of CD4+ or CD8+ T cells, or CD68+ macrophages." (PMID 35847718, 2020). "The pathologist graded CD68+ macrophage infiltration into tumour nests, irrespective of the overall immune cell infiltration within the ROI and without controlling for tumour nest size." (PMID 33122646, 2020). "Immunohistochemically, the tumor cells are positive for NKI-C3 (CD63) and CD68, but negative for melanocytic and epithelial markers." (PMID 32316685, 2020). "Immunohistochemistry study revealed that the tumor cells were positive for CD4 and CD30, and were negative for cytokeratin, CD3, CD20, CD68, CD163, lysozyme, ALK, S-100, and desmin." (PMID 32547956, 2020). "Using a customized immune panel of 36 antibodies, the researchers found that tumour infiltration by M2 macrophages (CD163 and CD68) had a significant negative impact on prognosis." (PMID 32917035, 2020). "Our results, indicating a prognostic significance of high infiltration of CD68+ and CD163+ macrophages in tumor nest, rather than the total infiltration, highlight the importance of considering the compartmental localization of TAMs in the TME." (PMID 33194593, 2020). "Furthermore, the molecular mechanism of CSF1/CSF1R in OSA remains unclear; the positive correlation with the expression of CSF1R and CD4/CD68 is not clear that it must play the positive effect on prognosis, and it may also be as a cancer promoting factor that involved in tumor immune escape." (PMID 32850346, 2020). "Multiplexed immunofluorescent staining including CD68 and CD206 and multi-spectral imaging were performed for the tumor tissues from 17 T-NHL patients without chemotherapy." (PMID 32385351, 2020). "The change in macrophage markers at the TS interface was investigated using the mean expression of CD68, CD163 and CD206 of tumor (AE1AE3+) and non-macrophage (other) cells as baseline thresholds." (PMID 31477692, 2019). "Upon stratification based on the median cell count per mm2 in the tumor area, a numerical but not significant trend towards a lower rate of DFS was observed in patients with high CD68+ infiltrate (hazard ratio 1.88, 95% CI 0.83–4.26, p = 0.13)." (PMID 30868392, 2019). "In all cases, the tumor cells were immunoreactive for CD34, desmin, smooth muscle actin (SMA), and estrogen receptor (ER) and negative for cytokeratin, p63, CD68, and beta-catenin." (PMID 30989009, 2019). "In all of our MFB cases, the tumor cells were immunoreactive for CD34, desmin, SMA, and ER and negative for cytokeratin, p63, CD68, and beta-catenin." (PMID 30989009, 2019). "Intriguingly, we found that CD68 and CD163 were mainly expressed at the tumor invasive front and stroma, with no to weak expression in tumor nest." (PMID 30927925, 2019). "In contrast, CD68+ M and CD47 expression did not correlate with most of the clinico-pathological variables, such as histological grade, clinical stage, tumor diameter, vascular invasion, and postoperative chemotherapy." (PMID 31771616, 2019). "Here, we observed that high DFO supplementation reduced the CD68 expression without increasing the CD163 expression (M2), despite the increase in apoptotic tumor cell fraction." (PMID 31413815, 2019). "CD68- and CD163-positive cells were not correlated with tumor size (CD68, P = 0.19; CD163, P = 0.27) or HER2 expression status (CD68, P = 0.33; CD163, P = 0.18)." (PMID 31528210, 2019). "The presence of few microglia in the GBM tumor sample were detected by IBA1 staining and few macrophages with CD68, which did not overlap with the TLRs positive tumor cells." (PMID 29912993, 2018). "Naïve alveolar macrophages, M0 type (CD68+CD206−IL12−) were substantially increased in BAL, but not within the tumor." (PMID 29520483, 2018).
tumor (continued). "It seems that HIV status has no impact on the local tumor immune microenvironment, including immune cell subset (CD3, CD4, CD8, and CD68) infiltration or PD-L1 expression." (PMID 29681240, 2018). "In contrast to the prevalence of CD163+ macrophages in tumor-bearing HSC-NOG-hIL-6 Tg mice, the frequency of CD163+ cells in intratumoral CD68+ cells was low in HSC-NOG non-Tg mice despite the small numbers of infiltrating human macrophages." (PMID 29456539, 2018). "Tissue biomarkers that did not stratify survival include MVD, tumour infiltrating T-cells and macrophages (CD3 and CD68 respectively), and the cell proliferation marker Ki67." (PMID 29535825, 2018). "CD11b+ and CD11c+ pixels were identified at a 240-micron distance, while CD68+ and CD163+ pixels did not exist more than 180 microns away from the tumor." (PMID 30619287, 2018). "PD-L1 expression co-localized with CD68 and CD163, supporting the idea that in our cohort PD-L1 is not mainly expressed by tumor cells but by myeloid cells." (PMID 28344870, 2017). "Infiltration of TAMs CD68+/iNOS− and Tregs CD8+/FoxP3+ in the tumor stroma are negative prognostic factors with a positive correlation between them." (PMID 28343267, 2017). "We further characterized the spatial distribution of the HLMs in the tumor and compared this non-standard tumor macrophage marker (iron(III)) with a common macrophage immunohistochemical marker, CD68." (PMID 28912459, 2017). "Eight cycles of NAC, on the other hand, did not alter the level of infiltration by CD68+ and CD163+ TIMs in post-NAC tumour specimens when compared with pre-NAC specimens." (PMID 28913366, 2017). "We found that CD68+CD206+ M2Mφs were mainly localized in peritumoural areas and that their number in tumours after irradiation was significantly higher than those in non-irradiated controls." (PMID 27271009, 2016). "Consistently, the number of S100+ DCs, but not that of CD68+ macrophages, positively correlated with the proportion of FcγRIIlow/− B cells in HCC tumours." (PMID 27853178, 2016). "Specifically, CD68+ cells were mainly located at the stroma of HER2+ samples and were not in contact with tumor cells, whereas CD68+ cells were found between cancer cells in the majority of TNBC samples." (PMID 27713152, 2016). "Immunohistological studies revealed that the tumor yielded positive staining for p63, vimentin, CD34 and CD68, but was negative for SMA, CD38 and cytokeratin." (PMID 25120721, 2014). "Immunostains were performed in which the viable adrenal cortical tumor cells expressed AE1/3 (weak, diffuse), melan A (strong, diffuse), and inhibin (moderate, diffuse), but were nonreactive for PAX8, CAIX, CD68, and CD163." (PMID 25108298, 2014). "The total number of macrophages in tumor tissue did not correlate with OS in both groups, however, the CD163/CD68 ratio correlates with OS in the total patient group." (PMID 25192022, 2014). "In our case, the tumor cells were positive for vimentin, CD10, and pancytokeratin, but negative for CK7, CEA, chromogranin, synaptophysin and CD68." (PMID 23305230, 2013). "Immunohistochemically, the tumour cells were positive for chromogranin and CD56, focal positive for S100, and negative for desmin, CD68, actin, SMA, and AE1/AE3." (PMID 22792486, 2012). "Immunostaining showed that the tumor was positive for the Vimentin, Bcl-2 and CD34, and was negative for S-100, desmin, CD68, and α–SMA." (PMID 23148444, 2012). "The tumor cells expressed CD1a, Langerin (CD207), S-100 protein, CD68 and vimentin, and did not express pan-T or B cell markers and epithelial markers." (PMID 22889043, 2012). "The tumor cells were negative for CD34, CK 5/6, CK7, CK20, S100, desmin, α–SMA, CD45, CD30, CD68 and HMB45." (PMID 22943673, 2012). "Conversely, tumor-infiltrating T cells show a negative correlation with VEGF, B7-H1/PD-L1, CD68+ macrophages and the endothelin B receptor." (PMID 18923710, 2008).
tumor (continued). "While CD68+ macrophages were neither increased nor decreased in limited or advanced stages, both S100 DC and CD163 macrophages were increased in the tumor stroma in limited disease (UICC I +II) compared to advanced disease (UICC III + IV)." (PMID 18047662, 2007). "The histological grade of the tumour did not correlate with the IL10 expression, nor did CD3 or CD68 expression." (PMID 11870535, 2002). "Further literature analysis indicated the nonspecificity of symptoms in patients with this tumor localization and variability in CD45 and CD68 staining in tumor cells, with consistent lack of expression of CD21, CD23, CD35, CD1a, and specific T- and B-cell antigens." (PMID 39171855, 2026). "In our study, however, there was a low co-localization of the CD68 and PTX3 in the tumor microenvironment, suggesting that PTX3 was mainly produced by tumoral cells, other immune cells, or stromal cells rather than the CD68-positive macrophages that were highly infiltrating the tumors." (PMID 41373493, 2025). "Interestingly, we found that CD68 and CD163 did not differentiate the two subtypes, with a similar number of positive cells in both the tumor parenchyma and the surrounding nontumorous tissue." (PMID 38611048, 2024). "The tumor cells were negative for CD25, myeloperoxidase (MPO), CD34, CD123, CD138, and CD163 but strongly positive for CD117, CD13, and CD33 and focally positive for mast cell tryptase, CD30, CD43, and CD68." (PMID 39404971, 2024). "However, hormone-related genes (BAG1, BCL2, CD68, ESR1 (ER), GSTM1, PGR, SCUBE2) do not show significant differential expression among all tumor samples." (PMID 38254834, 2024). "Similarly, mainly NPC cell, but not CD68+ CD86+ M1 and CD68+ CD206+ M2 macrophage-derived PD-L1 protein was increased in tumor samples from responders." (PMID 38448521, 2024). "This tumour did not express CD4, CD21 or fascin and had only variable expression with CD68." (PMID 36344905, 2023). "At early stages of tumor response (i.e., when tumor’s progression stopped), we indeed showed that Lipo-MP-LPS induces an early tumor infiltration by CD3+CD4+CD25+ T helper cells, but not Treg, and increases the levels of CD68+CD86+ M1 macrophages in tumors." (PMID 37760603, 2023). "By quantitative immunohistochemistry we found that cisplatin-based NACT has not resulted in the biologically significant decrease of total amount of CD68+ TAMs and amount of CD206+ and stabilin-1+ M2-like TAMs in the remaining tumor tissue compared to the non-treated tumor." (PMID 36960065, 2023). "We finally established using immunofluorescence studies with anti-CD68, anti-arginase and anti-CD206 that the combined treatment leads to the activation of TAMs with an M1 phenotype directly into the tumor spheroids whereas TAMs express an M2-like phenotype without treatment." (PMID 33402730, 2022). "In addition, to determine how the lack of IGF1R in the lung TME is conditioning tumor growth and metastasis, we performed double fluorescence immunostainings of p-IGF1R with CD68 (TAMs) and FOXP3 (FOXP3+ TILs) in lung sections from LLC-challenged mice." (PMID 35688943, 2022). "A wide range of immunohistochemical stainings were performed, such as CD68, SMA, desmin, EMA, mucin 4, SOX10, S100 and CD34, from which we could not deduce a specific differentiation line of the tumor cells." (PMID 35645621, 2022).